AKT1 (AKT serine/threonine kinase 1)
Diseases named in the same sentence as AKT1 in open-access papers (continued):
Sharing a sentence is not in itself a finding about the gene and the disease.
cancer (continued). "The PI3K/AKT signalling pathway is a major signalling pathway associated with cancer proliferation and metastasis at the genetic level, leading to the activation and recruitment of the AKT serine/threonine kinase 19,20." (PMID 37056382, 2023). "In cancer cells, AKT1 is implicated in proliferation and growth, promoting tumor initiation and suppressing apoptosis, while AKT2 regulates cytoskeleton dynamics, favoring invasiveness and metastatization." (PMID 36835056, 2023). "Dysregulation in the AKT1 gene, such as mutations, altered the function and/or its protein expression, thus modifying the response and sensitivity to cancers." (PMID 36982429, 2023). "As the mutations in AKT1 protein have been associated with different types of cancer, the association of highly deleterious AKT1 missense SNPs predicted in this study with cancer was further explored." (PMID 37511907, 2023). "Based on the combined score of each interaction with 0.4 confidence, the top 3 significant cancer-related signaling pathways in association with HDAC6 were Akt1 (0.704), MAPK1 (0.584), and TNF (0.403)." (PMID 36639650, 2023). "This study also aims to determine the association of these highly deleterious AKT1 missense SNPs with different cancers." (PMID 37511907, 2023). "It is worth mentioning that large-scale genomic studies of human cancer demonstrated that AKT1-E17K is the most common AKT mutation and improves the efficacy of AKT inhibitor therapy in solid tumors." (PMID 36765661, 2023). "AKT1 is a leading drug target for EOC and other cancers where AKT1 phosphorylation status is linked to poor survival outcomes in patients." (PMID 35269443, 2022). "The level of AKT1 expression and kinase activity is often associated with the degree of differentiation, hormone dependency, and aggressive behavior of cancer cells and/or with a less favorable prognosis." (PMID 36365115, 2022). "Overexpression of AKT isoforms is associated with multiple human cancers, and AKT1 is a prime drug target that is hyper-phosphorylated and overactive in most human cancers." (PMID 36497091, 2022). "Previous studies have also shown that AKT1 mutations are found in ~1% of all cancers, and the most prevalent mutant AKT1(E17K) leads to its localization to the plasma membrane, invoking a consistent activation of AKT signaling in cancer cells." (PMID 35892586, 2022). "Akt1 belongs to the most commonly activated proliferation signaling pathway in cancer, and the E17K mutation located in the canonical PIP binding pocket of the PH domain is oncogenic, as it increases membrane affinity and therefore Akt1 activity." (PMID 35857458, 2022). "The most significant pathways that involve GIP-9-like motif-containing proteins included constitutive signaling mediated by Akt1 carrying the E17K mutation, which is implicated in cancer." (PMID 35629968, 2022). "In cancer-related studies, excessive activation of Akt1 and Akt3 is the cause of some tumors in somatic cells." (PMID 35330934, 2022). "For example, Nucleolysin TIA-1 isoform p40 variant TIA1:61 was found downregulated in the AKT1 silenced sample compared to control (siNoN), which was reported downregulated in human cancers." (PMID 35892586, 2022). "Genetic alterations of the three Akt isoforms (Akt-1, -2, -3) have also been observed in some cancers, including E17k mutations in Akt-1, and amplifications of the genes encoding Akt-1 and -2, and PI3KCA have also been observed." (PMID 35954497, 2022). "We enrolled a total of twelve patients across eight different cancer types, including six patients with non-AKT1 E17K mutations (AKT1 D323G, E40K, L52R; AKT2 E17K, L78-Q79ins(HANTFVIRCL); AKT3 E17K) in this signal-seeking pilot study." (PMID 35440569, 2022).
cancer (continued). "RAC-alpha serine-threonine kinase (AKT1) is considered as an attractive drug target because its prolonged activation and overexpression are associated with cancer progression and metastasis." (PMID 35887580, 2022). "We found in 2 CTCs (50%) the nonsynonymous SNV AKT1 E17K (rs121434592), reported as pathogenic in several cancer types including BC and associated with resistance to therapies." (PMID 36010918, 2022). "AKT1 is a critical receptor for the activation of the highly cancer-causing Wnt/β-catenin signaling pathway, which is linked with cancer development." (PMID 36351994, 2022). "in cancer cells, activating mutations in PIK3CA and AKT1 genes, major players of PI3K-AKT-mTOR signalling pathway, are widely reported in many cancers and present attractive targets for the identification of new therapeutics and better cancer management." (PMID 35317488, 2022). "CEA acts as a paracrine factor, activating human fibroblasts by signaling through both STAT3- and AKT1-mTORC1 pathways, promoting their transition to the cancer-associated fibroblast phenotype, and enhancing cell migration." (PMID 34089362, 2021). "The growth factor–mediated PI3K/Akt/mTOR axis is a frequently activated pathway in cancer cells due to AKT1 mutation, loss of PTEN, or PI3K activator mutation." (PMID 34658867, 2021). "In cancer models, this nutritional stress translates into a reduction in growth through decreased deposition of H3K4me3 on promoters of the cancer-associated genes AKT1, MYC, and MAPK." (PMID 34804127, 2021). "Among various kinases, overexpression of AKT1 protein and associated mutations play a deciding role in cross-talk cell signalling in causing cancer." (PMID 34727985, 2021). "The oncogenic AKT1E17K, the most common AKT1 mutation, occurs infrequently in many types of cancers." (PMID 34419139, 2021). "We have now determined the crystal structure of Akt1, revealing an autoinhibitory interface between the PH and kinase domains that is often mutated in cancer and overgrowth disorders." (PMID 34385319, 2021). "PETN~BRAF sequential mutations were significantly more common than AKT1~BRAF sequential mutations in hypermutated cancers." (PMID 34503126, 2021). "Precision medicine is becoming important in the treatment of cancer, and the AKT1 mutation is a promising target." (PMID 34670536, 2021). "Through the network, we identified the most significant protein (Akt1) associated with the occurrence and development of cancer and a bioactive (Urs-12-en-24-oic acid, 3-oxo-, methyl ester) from the C. maackii flower." (PMID 34641448, 2021). "While 60% had further alterations, other than AKT1 mutation, which likely contribute to cancer development (e.g., truncating mutation in tumor suppressor or gain of oncogenic mutations)." (PMID 33854067, 2021). "The reduction in cancer development associated with Akt1 loss occurred with an increase in apoptosis and with the recruitment or expansion of a CD209a-expressing dendritic population." (PMID 33110146, 2020). "In case susceptibility analyses were performed in these studies, the AKT1 rs3803304 minor allele was associated with increased cancer susceptibility in all, confirming the contribution of the minor C allele in the etiology of multiple cancer types." (PMID 33112820, 2020).
cancer (continued). "As we linked all the interactions between the core-clock genes, cancer hallmarks and circadian drug target genes, we observed that AKT1 and MTOR were circadian expressed, drug target genes, in both cell lines." (PMID 32295075, 2020). "One of the interesting candidate genes identified in our study—Akt1 is both a cancer hallmark and a relevant circadian drug target gene." (PMID 32295075, 2020). "In particular, we showed that MTOR and AKT1 are oscillating in our data sets and associated to the circadian clock, cancer hallmarks and circadian drug targets." (PMID 32295075, 2020). "Of interests, five out of the 10 BRCA1/2 germline variants harboring cases were observed in complex carcinomas suggestive of tissue type-specific mutations along with AKT1 somatic mutations." (PMID 32680987, 2020). "Overactive AKT1 in cancer cells has been associated with driving cells into senescence (an aging cell state characterized by permanent cell cycle arrest)." (PMID 30875364, 2019). "On the other hand, AKT1 expression is linked to survival, proliferation and formation of mammospheres formed out of cancer stem cells as well as maintaining the EMT-phenotype with high vimentin and low E-cadherin and FAK expression." (PMID 31752925, 2019). "Cancer-associated fibroblasts have the ability to increase AKT1 activation in mammary epithelial cells through direct cell-cell-contact and therefore silencing of the tumor suppressor Cystatin M via promotor hypermethylation." (PMID 31752925, 2019). "AKT1 hyperactivation is implicated in many cancers and generally indicates an unfavorable prognosis." (PMID 31405032, 2019). "Disruption of the PH and kinase domain interaction was identified as a plausible cause of increased Akt1 phosphorylation and subsequent activity in cancer." (PMID 30205513, 2018). "Mutations in cancer related genes, including Akt1 and EGFR, and intratumoral heterogeneity can induce chemotherapy resistance." (PMID 30111862, 2018). "For example, MAPK3, transforming protein p21 (HRAS), and v-akt murine thymoma viral oncogene homolog 1 (AKT1) were all reported as highly related to the MAPK signaling pathway (KEGG ID: map 04010) known to be associated broadly with many cancers." (PMID 30255812, 2018). "Cancer cell lines or patient-derived tumors harboring PIK3CA or AKT1-E17K mutations exhibited increased sensitivity to ARQ 092 treatment." (PMID 29549527, 2018). "Here we show for the first time that endothelial-specific loss of Akt1 promotes cancer metastasis in vivo involving β-catenin pathway." (PMID 29755115, 2018). "Since the frequency of mutations including E17K in cancer patients was highest in Akt1, we focused on Akt1 in our genetic study." (PMID 28209968, 2017). "A diagnostic assay for the AKT1 E17K mutation will facilitate assessment of clinical activity of the pan-AKT inhibitor AZD5363 in advanced cancer patients whose tumor harbors this oncogenic mutation." (PMID 28472036, 2017). "AKT1 encodes a serine-threonine protein kinase which is activated by platelet-derived growth factor which has been implicated in many cancers, with the highest incidence in breast cancer." (PMID 28589855, 2017). "In the recent years, the PH domain of AKT1 has been implicated as an important target for development of anti-cancer therapy." (PMID 27626683, 2016). "Activation of Akt1 is associated with the proliferation, angiogenesis, growth and survival of cancer cells." (PMID 27588471, 2016). "The underlying mechanism for the observed association of cancer risk associated with rs2494752 SNP was that the rs2494752 G allele significantly increased the transcriptional activity of AKT1." (PMID 26818920, 2016).
cancer (continued). "For example, while mTOR and E2F1 are the top-ranking oncomodules associated to mutations of MLL2 in HNSC, we found that oncomodules in the MEK/AKT1 axis are top-ranking in association to NSD1 mutations in the same cancer type." (PMID 27095575, 2016). "Activation of AKT1 (p-Akt)was associated with poor prognosis in cancers like esophageal squamous cell carcinoma." (PMID 26437640, 2015). "With the goal of identifying allelic variants that significantly contribute to pathogenesis and smoking-related traits, global tests of associations were performed between each SNP of the AKT1 gene and cancer predisposition and smoking behaviors." (PMID 26137473, 2015). "In this work we focussed our study on investigating the changes in dynamic behaviour of AKT1 PH domain induced by the cancer causing E17K mutation." (PMID 23741320, 2013). "Recently it has been shown that E17K mutation in the Pleckstrin Homology (PH) domain of AKT1 protein leads to cancer by amplifying the phosphorylation and membrane localization of protein." (PMID 23741320, 2013). "The researchers investigated the interactions between DAF-2 (an insulin/IGF-1 homolog associated with aging), CEP-1, and AKT-1 (a protein that belongs to the Protein Kinase B/AKT family of protein kinases that are implicated in a wide range of human cancers)." (PMID 24151577, 2013). "EGFR, FGFRs, PIK3CA, PIK3R1 and AKT1 are proto-oncogenes, frequently activated in cancer through gain-of-function mutations and/or overexpression." (PMID 24213504, 2012). "We analysed the presence of the AKT1 E17K mutation in 731 cancer tissues by a single-strand conformation polymorphism assay." (PMID 18392055, 2008). "Thus, in this study, we have performed high-throughput analyses of the proteins and transcripts deregulated after mild overexpression of human WT and mutated AKT1 variants in Drosophila, which is a powerful yet-simpler-than-mouse model for studying cancer." (PMID 41237900, 2025). "Therefore, several studies have documented the efficacy of capivasertib in managing hormone receptor-positive breast cancer and tumors harboring AKT1 mutations, highlighting its potential as a pivotal component in targeted cancer therapy." (PMID 39099917, 2024). "AKT exists in three isoforms: Among these, AKT-1 is primarily associated with cancer." (PMID 38504785, 2024). "Many studies have investigated how mutations at the interface between the domains disrupt autoinhibition—in this instance—mutations cause AKT1 to enter a hyperactive state, which is associated with cancer and disorders associated with unregulated cell proliferation." (PMID 39192607, 2024). "There are three members of the Akt family, but only Akt1 is implicated in cancer development." (PMID 38672636, 2024). "AKT1 mutations are much less common than PIK3CA mutations among childhood cancers." (PMID 39510293, 2024). "The AKT1 gene in an oncogene and mutations in it can cause cancer." (PMID 37511907, 2023). "The authors suggested that 15 and its analogues could be valuable for studying AKT1 biological functions and developing drugs to treat AKT-associated human cancers." (PMID 37513905, 2023). "The main Akt isoform is encoded by the Akt1 gene; it was shown that each Akt isoform is differentially expressed at both the mRNA and protein levels, and each one exerts different roles not only in a physiological context but also in cancer pathogenesis." (PMID 36769122, 2023). "AKT1-rs10138227 has previously been associated with cancer status and smoking duration and may be associated with psychiatric disorders." (PMID 36152082, 2023). "AKT1 is also implicated in the increased migratory capacity of cancer, so it was unsurprising to see that the overexpression of miR-143-3p significantly reduced migration in RWPE1, DU145 and PC3 cell lines, while the inhibition of miR-143-3p significantly increased migration in RWPE1 cell lines." (PMID 37759434, 2023).
cancer (continued). "Hence, cancer cells with ARID1A mutation or deficiency depend more on the PI3K/Akt1 pathway than the cells expressing normal ARID1A." (PMID 36910637, 2023). "The mutations in the AKT1 gene have been associated with different types of cancer." (PMID 37511907, 2023). "Interestingly, decreased growth rate was observed in cancer cells overexpressing lysine 14-mutated AKT1 compared to cells overexpressing wild-type AKT1." (PMID 35495117, 2022). "While both regulatory phosphorylation sites in AKT1 (T308, S473) are associated with disease and used as clinical markers, in some cancers high levels of T308 phosphorylation are associated with poor prognosis, while in other cancers, poor survival correlates with high pS473 levels." (PMID 35269443, 2022). "However, upon EGF stimulation, we observed 10 examples of spliced variants downregulated upon AKT1 silencing, among them many were reported with an alteration related to breast/human cancers." (PMID 35892586, 2022). "However, there exists a long right tail of less frequent somatic AKT1 mutations of uncertain biological and therapeutic significance that we routinely observe in advanced cancers, but lack the information to act clinically." (PMID 35440569, 2022). "Besides, activation of the PI3K pathway or inactivation of PTEN can cause AKT1 activation in cancers." (PMID 35402264, 2022). "Another study was published in Clinical Cancer Research in 2020, which compared capivasertib monotherapy and combination therapy of capivasertib plus fulvestrant in ER‐positive metastatic breast cancer with AKT1 mutation." (PMID 38089455, 2022). "Importantly, each variant’s ability to drive Akt1 Thr308 phosphorylation correlated with the variant’s incidence in cancers (Pearson’s r: 0.76)." (PMID 34649609, 2021). "Another study also reported an association between the AKT1 polymorphism and cancer metastasis." (PMID 34150619, 2021). "The phosphorylation of AKT1 is associated with cell proliferation and inhibition of apoptosis in several malignancies, since it regulates downstream targets, which promote angiogenesis and cancer progression." (PMID 34205978, 2021). "AKT1 mutation occurs in many cancers at a low prevalence (1% across diverse solid tumors)." (PMID 34419139, 2021). "Increased AKT1 activity is associated with a variety of cancers, including OC." (PMID 35004651, 2021). "Hence, we aimed to determine the frequencies and relationships between clinicopathological features and AKT1 mutations in Asian women with cancer." (PMID 34670536, 2021). "Some AKT1 substrates are causative agents in pathologies such as cancers or diabetes." (PMID 33614606, 2020). "Mutations of PIK3CA (6–35%) are more frequent in cancers as compared to AKT1 mutations (0–8%)." (PMID 29549527, 2018). "We have already shown that S129 phosphorylation, besides upregulating active Akt1, is instrumental for the recognition of palladin, an actin-associated protein involved in cancer cell migration and invasion, suggesting its implication in the determination of substrate selectivity." (PMID 29494643, 2018). "Akt1 is associated with altered cell invasion and migration, and is a frequently activated protein kinase in cancers where it enhances the invasion capability of cancer cells." (PMID 28991210, 2017). "Initial reports suggested a prominent role for AKT1 in PTEN-deficient cancers." (PMID 28082369, 2017). "Previous studies have investigated associations between genetic variations in PTEN/PI3K/AKT signaling pathway and cancer risk, however, the association between PTEN rs701848, PIK3CA rs2699887, and AKT1 rs2494752 polymorphisms and sporadic BC in Chinese population has not been investigated yet." (PMID 28423632, 2017).